NCF1B (neutrophil cytosolic factor 1B (pseudogene) )
Synonyms: NCF-1B; SH3PXD1B
Gene: Long non-coding RNA gene on chromosome 7 (73,220,583 to 73,236,006, forward strand). Ensembl gene ENSG00000290838.
Diseases named in the same sentence as NCF1B in open-access papers:
NCF1B is named in the same sentence as 7 diseases in open-access papers, as found by Europe PMC text mining. Sharing a sentence is not in itself a finding about the gene and the disease. The quoted sentences say what the papers report.
sarcoma (2 papers, 2021 to 2022). A usually aggressive malignant neoplasm of the soft tissue or bone. "One bioinformatic analysis reported that the overexpression of the lncRNAs ADAM6, C5orf58, CXCR2P1, FCGR2C, HCP5, HLA-H, NAPSB, NCF1B, and NCF1C reduced the sensitivity of sarcoma to ICIs." (PMID 36326232, 2022). "The expression of nine ICLs, ADAM6, C5orf58, CXCR2P1, FCGR2C, HCP5, HLA-H, NAPSB, NCF1B and NCF1C, was further investigated in different cancer types, including sarcoma." (PMID 34178688, 2021).
bladder cancer (1 paper, 2022). "Several lncRNAs such as NCF1C, NCF1B, CXCR2P1, LINC02446, and AC0048473.1 have a high number of target genes that are associated with immune function, indicating that these lncRNAs are functionally related to immune activation in bladder cancer." (PMID 36091015, 2022).
chronic granulomatous disease (1 paper, 2022). Chronic granulomatous disease (CGD) is a rare primary immunodeficiency, mainly affecting phagocytes, which is characterized by an increased susceptibility to severe and recurrent bacterial and fungal infections, along with the development of granulomas. "For example, chronic granulomatous disease (CGD) is caused by the chimeric form of NCF1 (neutrophil cytosolic factor 1) and its pseudogenes NCF1B (neutrophil cytosolic factor 1B pseudogene) and NCF1C (neutrophil cytosolic factor 1C pseudogene)." (PMID 35012455, 2022).
pancreatic cancer (1 paper, 2020). "Only 3 pseudogenes (NAMPTP1 NCF1B NCF1C) were remarkably upregulated in pancreatic cancer samples compared to normal controls." (PMID 33027767, 2020).
skin cancer (1 paper, 2020). "In addition to the mutations in genes known to be associated with skin cancer development, we identified multiple new UV target genes that harbor high frequency of T > C conversions, including GVINP1, NCF1B, FLG2, and SPEF2." (PMID 32188867, 2020).
cancer (2 papers, 2020 to 2021). A tumor composed of atypical neoplastic, often pleomorphic cells that invade other tissues. "Using GEPIA database, three (NAMPTP1 NCF1B NCF1C) out of 92 predicted pseudogenes were found to be remarkably upregulated in cancer samples." (PMID 33027767, 2020).
NCF1B also shares sentences with these, for which no sentence is quoted: infection (1 paper).